RN7SKP42 (RN7SK pseudogene 42)
Gene: Miscellaneous RNA gene on chromosome 2 (187,122,562 to 187,122,861, reverse strand). Ensembl gene ENSG00000222845.
Homologues: Orthologues: chimpanzee 7SK (99% identical), guinea pig 7SK (62% identical), guinea pig 7SK (57% identical), mouse Gm56212 (49% identical). Paralogues in human: RN7SKP79 (71% identical), RN7SKP255 (69% identical), RN7SKP6 (69% identical), RN7SKP95 (68% identical), RN7SKP47 (68% identical), RN7SKP20 (68% identical), RN7SKP294 (67% identical), RN7SKP71 (67% identical), RN7SKP90 (67% identical), RN7SKP163 (67% identical), RN7SKP176 (67% identical), 7SK (66% identical), and 284 more.